NLRP3 (NLR family pyrin domain containing 3)
Diseases named in the same sentence as NLRP3 in open-access papers (continued):
Sharing a sentence is not in itself a finding about the gene and the disease.
periodontitis (continued). "After entering human periodontal ligament stem cells (hPDLSCs) by endocytosis, OMVs activated NLRP3 inflammasomes and impaired the mineralization of hPDLSCs through NF‐κB (p65) signaling, leading to the final injury of the periodontium and damage of alveolar bone in periodontitis." (PMID 39475060, 2024). "Recent studies have shown that NLRP3 and caspase‐4 inflammasomes in human periodontal ligament stem cells (PDLSCs) and gingival fibroblasts (GFs) can be activated under an inflammatory environment, resulting in pyroptosis and IL‐1β secretion, exacerbating periodontitis." (PMID 37710420, 2024). "Thus, it is hypothesized that Dioscin could be used to manage periodontitis by modulating the NLRP3 inflammasome." (PMID 38385066, 2024). "Besides, the activated NLRP3 inflammasome can also intrigue cell autophagy, promote the differentiation of osteoclasts and inhibit the osteogenic function of hPDLFs, finally promoting the periodontitis." (PMID 38191432, 2024). "BML-111 has been shown to play a pro-resolution role in inflammatory models such as acute lung injury, collagenous arthritis, and acute pancreatitis by activating the Nrf2/HO-1 pathway and inhibiting the NF-κB/NLRP3 signaling pathway, but its role in periodontitis remains unclear." (PMID 38191432, 2024). "Moreover, miR-30a-5p was responsible for inflammation and osteogenesis inhibition in periodontitis, and could drive NF-kB/NLRP3 signaling pathway to accelerate chronic heart failure." (PMID 38302986, 2024). "In addition, systemic diseases such as diabetes may enhance NLRP3 expression in patients with chronic periodontitis, with an increase in IL-1β production." (PMID 38817019, 2024). "Therefore, the downregulation of the NF-κB/NLRP3 axis might be involved in the anti-inflammatory effects of SB in periodontitis." (PMID 36846719, 2023). "Therefore, by modulating osteoclast activity and differentiation, the NLRP3 inflammasome may be exploited as a target to treat periodontitis through governing bone resorption." (PMID 36185327, 2022). "The compounds inhibiting leukotoxicity, the NLRP3 inflammasome or cell-to-cell communication, are well-known in the literature and could be explored regarding their application in the treatment of A. actinomycetemcomitans-mediated periodontitis." (PMID 35215102, 2022). "The differential expression of NLRP3 in neutrophils depending on their localization (peri-alveolar or peri-sulcus), and the presence or not of P. gingivalis, strongly suggests that several subtypes of neutrophils are recruited or differentially matured in periodontitis." (PMID 35281020, 2022). "Another study showed that periodontitis patients had higher serum and salivary NLRP3 concentrations in comparison to healthy controls, which means that periodontitis could be a significant predictor of both serum and salivary NLRP3 concentrations." (PMID 35265136, 2022). "Distinct and independent processes in NLRP3 inflammasomes in vitro are shown to elicit IL-1B and IL-18 production in response to non-canonical stimulation, which can fine-tune the pyroptosis response and is likely to account for the opposing patterns observed in periodontitis samples." (PMID 35844512, 2022). "Considering that EMD lowers the inflammation also in vivo and that periodontitis is linked to pyroptosis, we can speculate that EMD exerts its beneficial effect by reducing pyroptosis signalling at sites of chronic periodontitis, likely involving the NLRP3 expression." (PMID 35563469, 2022). "Therefore, whether NLRP3 or AIM2 inflammasomes are more predominant in A. actinomycetemcomitans-induced periodontitis remains unclear." (PMID 34177950, 2021). "Therefore, the effect of P. gingivalis on the NLRP3 inflammasome may be context-dependent in the pathogenesis and development of periodontitis." (PMID 34177950, 2021).
periodontitis (continued). "In the future, we may generate myeloid specific NLRP3‐overexpression or knockout mice by crossing NLRP3‐Tg mice or NLRP3‐floxed mice with Lysm‐cre or CX3CR1‐cre mice and then establishing ligature‐induced periodontitis in the absence and presence of the NLRP3 inhibitor, MCC950." (PMID 33382502, 2021). "In our study, the expression of inflammatory cytokines in OSCC showed that periodontitis-associated bacteria significantly (p < 0.05) upregulated IL-6, TNF-α, IL-18, ASC (up to six times), and caspase-1 (up to four times) but downregulated NF-κB, NLRP3, and IL-1β (less than 0.5 times)." (PMID 34660289, 2021). "Hence, increased DKK1 levels generated by osteocytes in osteolytic diseases, such as periodontitis, may also contribute to the increased activity of the NLRP3 inflammasome in these scenarios, although stronger, direct evidence is still needed." (PMID 34177950, 2021). "We speculate that activation of other Caspase-1 activating inflammasomes may compensate the inactivation of Nlrp3 in Nlrp3-KO mice, which may account for the lack of influence on bone resorption associated with experimental periodontitis in these mice." (PMID 32385413, 2020). "Moreover, the expression of TRPV1 and TLR4 found in keratinocytes, fibroblasts, inflammatory cells and capillary endothelial cells in patients with aggressive and chronic periodontitis suggests a role for TRPV1 signaling in the induction of the NLRP3 inflammasome." (PMID 25644504, 2015). "The NLRP3 inflammasome plays a central role in the initiation and progression of major OID, including periodontitis, pulpitis, periapical lesions, orthodontic and prosthodontic treatment complications, OLP, OSCC, and SS." (PMID 41596738, 2026). "The NOD-like receptor (NLR) family pyrin domain containing 3 (NLRP)-3 inflammasome, a supramolecular complex, plays an important role during the inflammatory response, such as in T2DM and periodontitis." (PMID 41009326, 2025). "In turn, periodontitis, in patients with T2DM, contributes, through its chronic inflammatory effects, to greater positive regulation of NLRP3 concentrations, both at the salivary and systemic levels." (PMID 41009326, 2025). "ROS production in response to LPS also activate the NLRP3 inflammasome by inducing OS‐related proteins like TXNIP and MAVS, which further drive periodontitis progression." (PMID 41298339, 2025). "The results revealed that the expression of NLRP3, IL‐1β, IL‐18, IL‐6, and TNF‐α was upregulated by F. nucleatum and its OMVs in rats with periodontitis." (PMID 39475060, 2024). "Single-cell sequencing of gingival tissues from periodontitis patients revealed three types of macrophages, including PRDM1 + Macro, NLRP3 + Macro, and C1QA + Macro." (PMID 38689292, 2024). "NLRP3 expression is elevated in the serum and saliva of periodontitis patients, and AIM2 expression has been confirmed in the gingival tissues of both periodontitis and gingivitis patients." (PMID 38921772, 2024). "Patients with severe periodontitis exhibit significant increases in the expression of interleukin-1β (IL-1β), tumor necrosis factor-α (TNF-α), nod-like receptor protein 3 (NLRP3), and their absence in melanoma 2 (AIM2) inflammasomes in the gingival tissues." (PMID 38921772, 2024). "LincRNA‐EPS inhibits the LPS‐induced production and activation of caspase‐11 and NLRP3 inflammasomes by suppressing the activation of the NF‐κB signalling pathway via interacting with TDP43, thereby alleviating periodontitis." (PMID 37710420, 2024). "Increased salivary levels of NLRP3, ASC, and IL-1β were also observed in systemic healthy patients with periodontitis, and diabetic patients with periodontitis, when compared with healthy periodontal patients." (PMID 38817019, 2024). "Periodontitis and HDL-cholesterol were significant predictors of serum NLRP3 while periodontitis and CRP were the significant predictors of salivary NLRP3." (PMID 38954692, 2024).
periodontitis (continued). "Then we used IHC staining to test the three most significant different genes from qPCR analysis(NLRP3, DLST and SLC3A1), evidence from IHC results showed that NLRP3 and DLST were significantly increased in the 10 periodontitis tissues than control samples." (PMID 37215133, 2023). "Immunostaining images showed a stronger signalling intensity for NLRP3, cleaved CAS1, and IL-1β in the connective tissue of periodontitis compared to a healthy gingiva." (PMID 35563469, 2022). "In the context of periodontitis, a number of recent in vitro and animal experimental studies have also documented the activation of GSDMD and NLRP3 inflammasome pathways, including that by P. gingivalis lipopolysaccharide (LPS) stimulation." (PMID 35844512, 2022). "NLRP3 expression in GCF and periodontal parameters were increased in patients with chronic periodontitis compared to those in healthy individuals but then decreased after 6 months of combined periodontal-orthodontic treatment." (PMID 34177950, 2021). "First, longitudinal studies are required to explore the role of NLRP3 (rs4612666) and CARD8 (rs2043211) as a therapeutic marker for both periodontitis and coronary heart disease." (PMID 34199122, 2021). "In this study, we intended to explore the effect of periodontitis-related bacteria on the biological behavior of OSCC, including the expression of inflammasome NLRP3 and the potential mechanism of regulating ATR-CHK1-dependent DNA damage in vivo." (PMID 34660289, 2021). "Along with increased IL-1β processing, the activation of inflammasomes, such as NLRP3 and AIM2, is frequently detected in chronic periodontitis and aggressive periodontitis." (PMID 34177950, 2021). "NLRP3 and IL1B genotypes and IL2 Haplotype Frequency Distributions in patients with periodontitis and controls." (PMID 31978095, 2020). "Regarding inflammasomes other than the NLRP3, it was demonstrated that NLRP6 was more highly expressed in gingival tissues of patients with periodontitis than in healthy controls." (PMID 31341421, 2019). "Interestingly, when researchers looked at gingival tissues rather than saliva, they found higher expression of caspase-1, NLRP3, ASC and AIM2 in patients with chronic periodontitis." (PMID 41440367, 2025). "Given the significance role of ROS and NLRP3 in the development of periodontitis, the ROS‐MAVS‐NLRP3 axis may become a potential avenue for future research as one of the pathogenesis and therapeutic targets of periodontitis." (PMID 41298339, 2025). "Mechanistically, mtROS may be involved in macrophage M1 polarization in periodontitis through activation of MAPK and NF-κB pathways, activation of NLRP3 inflammasome and stabilization of HIF-1α." (PMID 40861497, 2025). "Additionally, salivary levels of NLRP3, ASC, and IL-1β were higher in chronic or aggressive periodontitis patients than in healthy patients; however, levels of caspase-1 were not altered." (PMID 41440367, 2025). "We found significantly higher concentrations of NLRP3 in both saliva and serum among patients with periodontitis than in those without the disease." (PMID 40572711, 2025). "As we have observed in THP-1 derived macrophages, it is well established that NLRP3 and AIM2 are upregulated in saliva, periapical lesions and gingival tissues of periodontitis patients, driving an increase in IL-1β secretion." (PMID 40490723, 2025). "Significantly higher levels of NLRP3 in saliva (p = 0.038) and serum (p = 0.021) were observed in patients with periodontitis than in those without periodontitis." (PMID 40572711, 2025). "Search terms included combinations of “inflammasome,” “NLRP3,” “AIM2,” “IFI16,” “dental pulp,” “pulpitis,” “periodontitis,” “chronic oral inflammation,” “interleukin-1β,” “interleukin-18,” “oral squamous cell carcinoma,” “oral cancer,” “NF-κB,” “bacterial pathogens,” and related terms." (PMID 41440367, 2025).
periodontitis (continued). "Understanding the intricate interplay between Galectin-3, NLRP3, suPAR, CRP, and periodontitis requires further studies, which could lead to pivotal findings for elucidating disease mechanisms and identifying potential therapeutic targets." (PMID 39453923, 2024). "Among these genes NLRP3 and NFE2L2 related with periodontitis were reported." (PMID 37215133, 2023). "The overexpression of NLRP3 in gingival tissue has been proposed as a negative factor in the evolution of periodontitis." (PMID 35281020, 2022). "Study by Isola showed that, Non-Like receptor Family Pyrin domain containing protein 3(NLRP3), plays an important role in the development of periodontitis and diabetes." (PMID 35521636, 2022). "By inactivating the NLRP3 inflammasome in preclinical models, VD3 could attenuate osteoarthritis, periodontitis, and cutaneous inflammation." (PMID 36880085, 2022). "The aim of the current study is to better understand NLRP3 implication during the onset of periodontitis using the ligature method with or without P. gingivalis in NLRP3 knock out (KO) mice." (PMID 35281020, 2022). "Limited evidence in periodontitis revealed that P. gingivalis, Mycoplasma salivarium, Treponema denticola surface protein Td92, E. faecalis, and LPS can induce pyroptosis in macrophages through the NLRP3/caspase-1/GSDMD pathway, contributing to the pathogenesis and development of periodontitis." (PMID 36093182, 2022). "In our study, we use a periodontitis mouse model of ligature, impregnated or not with Porphyromonas gingivalis, in WT or NLRP3 KO mice." (PMID 35281020, 2022). "The level of NLRP3 inflammasome mRNA and its related proteins are increased in periodontitis and gingivitis, which corroborates a negative role of NLRP3 in the oral cavity." (PMID 34557201, 2021). "In addition to NLRP3 and AIM2, the effects of other canonical inflammasomes on the pathogenesis and development of periodontitis have also been investigated." (PMID 34177950, 2021). "This study had the objective of assessing NLRP3 (rs4612666) and CARD8 (rs2043211) gene polymorphisms in dental plaque and blood of generalized chronic periodontitis (CP) patients in the presence and absence of coronary heart disease (CHD)." (PMID 34199122, 2021). "Furthermore, the interaction of NLRP3+ macrophages and structural cells through TNF-TNFRSF1A and CXCR3_CCRL19 offered us a hint of the biological function of NLRP3+ macrophages in periodontitis." (PMID 34566966, 2021). "In order to observe the different distribution of NLRP family intuitively, immunohistochemistry was applied to analyze the expression characteristics of NLRP1, NLRP2, NLRP3, NLRP6, and NLRP12 in full-thickness gingival tissue samples obtained from severe periodontitis patients and healthy people." (PMID 32903638, 2020). "Furthermore, we found that the phosphorylation of NF-κB p65 and the expression of NLRP3, ASC and caspase-1 were increased in the gingival epithelium in periodontitis, while they were decreased upon VD3 treatment." (PMID 31691738, 2019). "Furthermore, the activation of both the NLRP3 and AIM2 inflammasomes is necessary for IL-1β secretion after stimulation with P. gingivalis, the main bacteria that induces periodontitis." (PMID 26078980, 2015). "Among patients with periodontitis, no predictive cutoff value could be established for any of the four pro-inflammatory markers regarding the presence or absence of periodontitis (NLRP3 in saliva and serum; IL-1β in saliva and serum)." (PMID 40572711, 2025). "(2015) reported that, both in patients with chronic periodontitis and T2DM, as well as human gingival epithelial cells (HGEC) stimulated with lipopolysaccharide (LPS) and high concentrations of glucose, showed a significant increase in the expression of the NLRP3 inflammasome and IL-1β." (PMID 40406515, 2025).
periodontitis (continued). "Though there are currently no direct studies linking FOXO to the NLRP3 inflammasome in periodontitis, research has shown that SIRT1 activation by SRT1720 promotes FOXO1 deacetylation, reduces ROS overproduction, and inhibits NLRP3 inflammasome activation in models of subarachnoid hemorrhage (SAH)." (PMID 41298339, 2025). "The role of non-canonical NLRP3 inflammasome activation in periodontitis needs further study." (PMID 35844512, 2022). "The balance between bone resorption and repair in periodontitis could therefore result from fine-tuning of the NLRP3 inflammasome, the overactivation or absence of which could lead to pathologic bone loss." (PMID 35281020, 2022). "In addition, it has been documented that, both in patients with chronic periodontitis and T2DM, and in human gingival epithelial cells (HGEC) exposed to lipopolysaccharide (LPS) and high glucose concentrations, a significant increase in the expression of the NLRP3 inflammasome and IL-1β is observed." (PMID 41009326, 2025). "It has been found that CA treatment of LPS-induced Human gingival fibroblasts (HGFs) inhibited NLRP3 expression and reduced IL-1β and IL-18 levels while increasing NRF2 and HO-1 expression and reducing oxidative stress, suggesting that CA could attenuate inflammation in HGFs during periodontitis." (PMID 39456522, 2024). "However, the effects of NLRP3 inflammasome on periodontitis have not been fully studied." (PMID 33382502, 2021). "In periodontal diseases, upregulation of IL-1β protein and NLRP3 inflammasome has also been demonstrated in periodontal tissues of uncontrolled type 2 diabetic patients with periodontitis, who exhibit more alveolar bone damage, compared with nondiabetic periodontitis patients." (PMID 31146750, 2019). "Porphyromonas gingivalis is considered a major etiologic agent of periodontitis and activates the NLR family pyrin domain containing 3 (NLRP3) but is absent in melanoma 2 (AIM2) inflammasomes, resulting in pro-inflammatory cytokine release." (PMID 38921772, 2024). "Both groups of periodontitis patients (CHC + P and P) expressed significantly elevated levels for all of the three assessed proinflammatory mediators (NLRP3, CASP1, and IL-18) as compared to the nonperiodontitis groups (CHC and H)." (PMID 34840527, 2021). "It is already known that the NLRP3 inflammasome and secretion of IL-1β are crucial for the development of PD, because in the absence of NRLP3 or IL-1β, there is no periodontitis induced by P. gingivalis in mouse models." (PMID 31341421, 2019). "Furthermore, various studies demonstrated increases in the expression of NLRP3, AIM2, IL-1β, and IL-18, but not ASC or NLRP2, in gingival tissue from periodontitis patients when compared to healthy individuals." (PMID 31341421, 2019). "On the other hand, in NLRP3-KO macrophages, the absence of the feedback loop reduces ROS levels and, although they maintain the ability to induce mtDNA release and activate AIM2, IL-1β secretion and pyroptosis are significantly decreased in both periodontitis and peri-implantitis scenarios." (PMID 40490723, 2025).